EXOSC5 (exosome component 5)
Description:
Non-catalytic component of the RNA exosome complex which has 3'->5' exoribonuclease activity and participates in a multitude of cellular RNA processing and degradation events. In the nucleus, the RNA exosome complex is involved in proper maturation of stable RNA species such as rRNA, snRNA and snoRNA, in the elimination of RNA processing by-products and non-coding 'pervasive' transcripts, such as antisense RNA species and promoter-upstream transcripts (PROMPTs), and of mRNAs with processing defects, thereby limiting or excluding their export to the cytoplasm. The RNA exosome may be involved in Ig class switch recombination (CSR) and/or Ig variable region somatic hypermutation (SHM) by targeting AICDA deamination activity to transcribed dsDNA substrates. In the cytoplasm, the RNA exosome complex is involved in general mRNA turnover and specifically degrades inherently unstable mRNAs containing AU-rich elements (AREs) within their 3' untranslated regions, and in RNA surveillance pathways, preventing translation of aberrant mRNAs. It seems to be involved in degradation of histone mRNA. The catalytic inactive RNA exosome core complex of 9 subunits (Exo-9) is proposed to play a pivotal role in the binding and presentation of RNA for ribonucleolysis, and to serve as a scaffold for the association with catalytic subunits and accessory proteins or complexes. In vitro, EXOSC5 does not bind or digest single-stranded RNA and binds to double-stranded DNA without detectable DNase activity.
Synonyms: RRP46; hRrp46p; Rrp46p; RRP41B; MGC12901; p12B; CABAC
Tractability: Small molecule: a structure with a bound ligand is known. PROTAC: ubiquitination databases record sites on it; its protein half-life has been measured.
Gene: Protein-coding gene on chromosome 19 (41,386,353 to 41,397,441, reverse strand). Ensembl gene ENSG00000077348.
Subcellular location: Nucleus, nucleolus; Cytoplasm; Nucleus
Subcellular location (Human Protein Atlas): Nucleoli; Nucleoplasm
Pathways (Reactome):
Metabolism of RNA: Butyrate Response Factor 1 (BRF1) binds and destabilizes mRNA; KSRP (KHSRP) binds and destabilizes mRNA; Major pathway of rRNA processing in the nucleolus and cytosol; Nuclear RNA decay; Tristetraprolin (TTP, ZFP36) binds and destabilizes mRNA; mRNA decay by 3' to 5' exoribonuclease
Cellular responses to stimuli: ATF4 activates genes in response to endoplasmic reticulum stress
Gene Ontology:
Molecular function: protein binding; RNA exonuclease activity; 3'-5'-RNA exonuclease activity; RNA binding
Biological process: defense response to virus; DNA deamination; mRNA catabolic process; RNA catabolic process; RNA processing; nuclear mRNA surveillance; poly(A)-dependent snoRNA 3'-end processing; rRNA catabolic process; rRNA processing; U4 snRNA 3'-end processing
Cellular component: cytosol; euchromatin; exosome (RNase complex); nucleolus; nucleus; cytoplasm; cytoplasmic exosome (RNase complex); nuclear exosome (RNase complex); nucleolar exosome (RNase complex); nucleoplasm; exoribonuclease complex
Genetic constraint (gnomAD): Loss-of-function variants: 11 observed, 16.02 expected, observed/expected ratio (o/e) 0.69, 90% interval 0.43 to 1.14. The upper end of that interval is the gene's LOEUF score, 1.14, which puts it in group 4 of 6, group 1 being the genes least tolerant of losing a copy. Missense variants: 292 observed, 290.39 expected, observed/expected ratio (o/e) 1.01, 90% interval 0.91 to 1.11. Synonymous variants: 134 observed, 122.58 expected, observed/expected ratio (o/e) 1.09, 90% interval 0.95 to 1.26.
Homologues: Orthologues: chimpanzee EXOSC5 (99% identical), macaque EXOSC5 (98% identical), pig EXOSC5 (90% identical), guinea pig EXOSC5 (89% identical), mouse Exosc5 (89% identical), rabbit EXOSC5 (89% identical), rat Exosc5 (77% identical), tropical clawed frog exosc5 (66% identical), zebrafish exosc5 (58% identical), Drosophila melanogaster Rrp46 (36% identical), Caenorhabditis elegans crn-5 (29% identical). Paralogues in human: EXOSC6 (29% identical), EXOSC4 (26% identical).
Diseases named in the same sentence as EXOSC5 in open-access papers:
EXOSC5 is named in the same sentence as 29 diseases in open-access papers, as found by Europe PMC text mining. Sharing a sentence is not in itself a finding about the gene and the disease. The quoted sentences say what the papers report.
colorectal cancer (6 papers, 2019 to 2022). A primary or metastatic malignant neoplasm that affects the colon or rectum. "In addition, upregulation of EXOSC4 and EXOSC5 expression has been reported in colorectal cancer, in which upregulated expression of EXOSC5 was associated with a worse prognosis." (PMID 34948199, 2021). "Although results have highlighted the oncogenic role of EXOSC5 in colorectal cancer, there have been few studies on the role and related molecular mechanism of EXOSC5 in solid tumors." (PMID 36293016, 2022). "High expression of EXOSC5 is predictive of poor prognosis in colorectal cancer, and correlated with the tumor size." (PMID 35371329, 2022). "At the molecular mechanism, EXOSC5 plays a crucial part in growth of colorectal cancer via activating the ERK and AKT pathways." (PMID 35371329, 2022). "The EXOSC5 was identified as a novel prognostic marker that can promote proliferation of colorectal cancer through activating the ERK and AKT pathways." (PMID 33133154, 2020). "Similarly, previous studies also identified the roles of EXOSC4 and EXOSC5 in predicting the prognosis of colorectal cancer and renal cell carcinoma, respectively." (PMID 36293016, 2022). "EXOSC5 could promotes growth of colorectal cancer through regulating ERK and AKT pathways." (PMID 33456353, 2021). "However, the molecular mechanism and biological role of EXOSC5 have not been explored in colorectal cancer (CRC)." (PMID 31380280, 2019).
gastric cancer (3 papers, 2022 to 2024). A primary or metastatic malignant neoplasm involving the stomach. "Taken together, EXOSC5 appears to play a vital part in the progression of cancer, which encouraged us to explore whether EXOSC5 is implicated in the oncogenesis of gastric cancer." (PMID 35371329, 2022). "A previous study demonstrated that the signal transducer and activator of transcription 3 (STAT3) signaling pathway played a key role in the proliferation of gastric cancer mediated by EXOSC5." (PMID 36293016, 2022). "Our results showed that knockdown of EXOSC5 inhibited gastric cancer cell lines proliferation, so we hypothesized that EXOSC5 may be pivotal for cancer cell cycle regulation." (PMID 35371329, 2022). "Moreover, EXOSC5 expression has been linked to an increase in cyclin D1 and a decrease in p21/p27 expression, which promotes cell proliferation through the regulation of the AKT/STAT3 pathway in gastric cancer." (PMID 38164180, 2024). "A previous study reported that the STAT3 signaling pathway was involved in the EXOSC5-regulated proliferation of gastric cancer, and the elevated phosphorylation of STAT3 was also shown in HCC tissues and cell lines, which could be inhibited by the down-regulation of EXOSC5 in the present study." (PMID 36293016, 2022).
renal cell carcinoma (3 papers, 2022 to 2025). "EXOSC5, recognized as a tumor suppressor, has been downregulated in various cancers, including renal cell carcinoma, and plays a critical role in signaling pathways like JAK-STAT, MAPK, and WNT, which are crucial for cancer progression." (PMID 39941055, 2025).
Arrhythmia (2 papers, 2023 to 2024). Any cardiac rhythm other than the normal sinus rhythm. "Importantly, mutations in the EXOSC5 gene have been linked to cardiac conduction defects, arrhythmias, and an increased risk of sudden cardiac death." (PMID 37891634, 2023).
colon cancer (2 papers, 2021 to 2022). "We have also simultaneously examined two well-known biomarkers for colon cancer, podolanin and EXOSC5, to better differentiate between healthy and cancerous tissues." (PMID 33917056, 2021). "The same pathways have been identified to be regulated by EXOSC5 in colon cancer as well." (PMID 33917056, 2021). "Two prognostic colon cancer biomarkers, namely podoplanin and exosome component 5 (EXOSC5), have been chosen to further verify tumor and normal tissue specimens: podoplanin mRNA level was significantly increased by 10-fold in tumor samples, and EXOSC5 by even 20-fold." (PMID 33917056, 2021). "In order to investigate whether ZP2, Ki67, podoplanin, and EXOSC5 share the same tissue distribution, immunohistological analysis of colon cancer specimens has been performed." (PMID 33917056, 2021). "Podoplanin and EXOSC5 were shown to be more highly expressed in colon cancer as well, although to a minor extent compared to our study, which could be due to a lower number of tissue samples." (PMID 33917056, 2021).
lung carcinoma (2 papers, 2019 to 2022). "By using ELISA assay, specific serological responses of EXOSC5 were found in 10–33% of patients with lung cancer, melanoma, and prostate cancer." (PMID 31380280, 2019).
Stroke (2 papers, 2023 to 2024). Sudden impairment of blood flow to a part of the brain due to occlusion or rupture of an artery to the brain. "Our research findings highlight the significance of genes associated with the UPR pathway, including ATF6, EXOSC5, EEF2, LSM4, NOLC1, BANF1, and DNAJC3, in the occurrence of stroke." (PMID 37891634, 2023). "In a previous study, EXOSC5 was suggested to play an important role in stroke." (PMID 39290696, 2024).
cerebellar ataxia (1 paper, 2024). A neurological syndrome characterized by clumsy and uncoordinated movement of the limbs, trunk, and cranial muscles. "We present a patient with an EXOSC5 mutation leading to the clinical phenotype currently known as CABAC syndrome (cerebellar ataxia, brain abnormalities, and cardiac conduction defects), including pontocerebellar hypoplasia, who also developed TMA." (PMID 39062862, 2024). "Here, we present an infant (female) with an EXOSC5 mutation (c.230_232del p.Glu77del) associated with the clinical phenotype known as CABAC syndrome (cerebellar ataxia, brain abnormalities, and cardiac conduction defects), including pontocerebellar hypoplasia, who developed renal TMA." (PMID 39062862, 2024).
colon adenocarcinoma (1 paper, 2019). "The result revealed that EXOSC5 was remarkably up-regulated in Colon Adenocarcinoma (COAD) and Rectal Adenocarcinoma (READ) tissues compared to normal tissues." (PMID 31380280, 2019).
COVID-19 (1 paper, 2023). A disease caused by infection with severe acute respiratory syndrome coronavirus 2. "Understanding the biology and functional significance of the four obtained genes (TRMT2A, EXOSC5, REXO2, and MESD) provides insights into the molecular processes associated with disease severity in COVID-19." (PMID 37347079, 2023).
osteosarcoma (1 paper, 2021). A usually aggressive malignant bone-forming mesenchymal neoplasm, predominantly affecting adolescents and young adults. "Expression of ABCA3, CTGF, and AMIGO2 were significantly higher in metastatic osteosarcoma samples compared to the primary osteosarcoma samples while the expression of PREB, FHIT, and EXOSC5 were significantly decreased in metastatic osteosarcoma samples." (PMID 34368151, 2021).
prostate adenocarcinoma (1 paper, 2021). "Patients with a higher expression level of EXOSC5 had a worse prognosis for KIRC, KIRP, BC, and prostate adenocarcinoma (PRAD)." (PMID 34933446, 2021).
tumor (10 papers, 2019 to 2025). "IHC staining indicated that overexpression of EXOSC5 was associated with worse prognosis, larger tumor size, and advanced tumor stage of CRC patients." (PMID 31380280, 2019). "Overexpression of EXOSC5 is significantly associated with tumor size as well as worse oncological outcomes." (PMID 31380280, 2019). "Analysis of The Cancer Genome Atlas (TCGA) database by using GEPIA2 webtool showed that the level of EXOSC5 mRNA was significantly higher in EC tumor tissues than in normal endometrial tissues." (PMID 38164180, 2024). "An evident correlation was also detected between EXOSC5 expression and tumor histological grade (grades 1-3) in EC specimens." (PMID 38164180, 2024). "The analysis of tumor sphere formation revealed that the knockdown of EXOSC5 reduced the primary and secondary tumor sphere numbers in both EC cell lines, indicating that EXOSC5 is involved in the self-renewal capability of EC-CSCs." (PMID 38164180, 2024). "Owing to its expression and immunogenicity in a broad variety of malignancies, EXOSC5 deserve more evaluation as a target for tumor immunotherapy." (PMID 35371329, 2022). "In order to verify this data, we elucidated EXOSC5 mRNA expression in Zhejiang cohort 1 (43 matched GC and adjacent non-tumor samples)." (PMID 35371329, 2022). "We found that all tumor cells share the vast majority of these mutations (i.e., they are clonal), including variants affecting genes previously associated with CRC progression (e.g., INPP1, CDC5L, ROR2, EXOSC5)." (PMID 35081992, 2022). "Upregulation of EXOSC5 was significantly correlated with tumor size and TNM stage." (PMID 35371329, 2022). "Moreover, EXOSC5 knockdown significantly suppressed the cell tumor growth and proliferation both in vitro and in vivo, and caused G1/S arrest." (PMID 31380280, 2019). "Overexpression of EXOSC5 in the LOVO cells significantly augmented tumor growth in vivo." (PMID 31380280, 2019). "Therefore, we suggested that EXOSC5 has an important role in the tumor progression in CRC through activating the PI3K/AKT and MAPK/ERK signaling pathways." (PMID 31380280, 2019). "Furthermore, high EXOSC5 expression positivity correlated with the tumor size (P = 0.001)." (PMID 31380280, 2019). "Tumor sphere culture methods were used on two EC cell lines (AN3CA and HEC1A) to enhance CSC subpopulations to further validate the enrichment of EXOSC5 protein expression in EC-CSCs." (PMID 38164180, 2024). "Herein, we found the upregulation of EXOSC5 mRNA and protein levels in HCC tumor tissues, and similar results were also found in HCC cell lines." (PMID 36293016, 2022). "EXOSC5 mRNA expression levels were determined in 53 matched CRC and adjacent non-tumor tissue samples by qRT-PCR." (PMID 31380280, 2019). "The mRNA expression of EXOSC5 was determined by qRT-PCR in 15 matched HCC and adjacent non-tumor tissues." (PMID 36293016, 2022).
cancer (9 papers, 2015 to 2025). A tumor composed of atypical neoplastic, often pleomorphic cells that invade other tissues. "Although, emerging evidence suggests a close association between EXOSC5 and the progression of various cancer, we still know little about it." (PMID 35371329, 2022). "Its mechanism involves histone acetylation changes, impacting cancer-related pathways such as those regulated by EXOSC5." (PMID 39941055, 2025). "Although the expression of EXOSC5 has been studied in different cancers, there are limited reports about the clinical relevance and functional roles of EXOSC5 in solid tumors." (PMID 35371329, 2022). "In this study, we used a straightforward approach to uncover the expression pattern and clinicopathological features of EXOSC5 in GC and its prognostic function with prognosis by integrative analysis of multiple cancer databases and clinical samples." (PMID 35371329, 2022). "Background and Objective: Exosome component 5 (EXOSC5) is a novel cancer-related gene that is aberrantly expressed in various malignances." (PMID 31380280, 2019). "Although EXOSC5 is a potential prognostic factor and oncogene in numerous cancer types, its functional roles and molecular mechanisms in ECs are largely unknown." (PMID 38164180, 2024). "The spheroid formation capability of EXOSC5-depleted EC cells treated with rhNTN4 was analyzed to examine whether EXOSC5 promotes cancer stemness through secreted NTN4." (PMID 38164180, 2024). "Overall, the results showed that EXOSC5 maintains cancer stemness via regulation of NTN4 secretion." (PMID 38164180, 2024). "Interestingly, growing evidence suggests the role of EXOSC5 in the progression of cancers." (PMID 36293016, 2022). "EXOSC5 upregulates NTN4 expression, activating c-MYC through the integrin β1/FAK/SRC pathway to sustain cancer stem cell activity." (PMID 41235257, 2025). "EXOSC5 knockdown diminished EC-CSC self-renewal and reduced expression of key cancer stemness proteins, including c-MYC and SOX2." (PMID 38164180, 2024). "This is supported by the DDX11, DKC1, EXOSC5, NOP56, and other genes showing differences in the most cancer types." (PMID 36698399, 2022). "An GC organoid-based functional model was assessed, and cancer cell CCK-8 assay, colony formation assay and flow cytometry were performed to reveal the role of EXOSC5 in GC cell proliferation and tumorigenesis." (PMID 35371329, 2022). "Moreover, downregulated cancer stemness proteins, including BMI1, c-MYC, and SOX2, were observed in EXOSC5 knockdown EC cells." (PMID 38164180, 2024). "In addition, EXOSC5, UTP14A, TWISTNB, and TBL3 were closely related to the occurrence or prognosis of several cancers." (PMID 35601016, 2022).
EXOSC5 also shares sentences with these, for which no sentence is quoted: acute myelogenous leukemia (3 papers); endometrial cancer (3); chronic myelogenous leukemia (2); hepatocellular carcinoma (2); melanoma (2); prostate carcinoma (2); adenoma (1); atherosclerosis (1); cervical carcinoma (1); genetic disorder (1); Insulin resistance (1); ischaemic stroke (1); Kawasaki disease (1); neuropathy (1); Rectal Adenocarcinoma (1).